C5AR1 (complement C5a receptor 1)
Diseases named in the same sentence as C5AR1 in open-access papers (continued):
Sharing a sentence is not in itself a finding about the gene and the disease.
cancer (88 papers, 2013 to 2026). A tumor composed of atypical neoplastic, often pleomorphic cells that invade other tissues. "This causes alterations in the pro-cancer characteristics of C5aR1+ mast cells and macrophages to inhibit the cytotoxicity of CD8+ T cells." (PMID 39958348, 2025). "This is likely to occur at least in part since C5aR1 inhibition attenuates pro-survival signalling to render cancer cells more susceptible to death following radiotherapy." (PMID 39765018, 2025). "A pan cancer multiomics analysis showed that the expression of C3/C5/C3AR1/C5AR1 is associated with the immune evasion signature, indicating the possible immune modulating role of complement proteins in HCC." (PMID 36341431, 2022). "Among the gene signatures, C3 and C5 are the most frequently mutated, while C3AR1 and C5AR1 are less frequently mutated across the cancer types." (PMID 34439277, 2021). "Our analysis of the single nucleotide variation in the gene signature revealed that C3, C5, C3AR1, and C5AR1 have mutation frequencies of 41%, 24%, 14%, and 9%, respectively, across the TCGA cancer types." (PMID 34439277, 2021). "We found that C3, C5, C3AR1, and C5AR1 were frequently mutated (9~41%) in the studied cancer cohorts." (PMID 34439277, 2021). "We conducted a gene pathway activity and interaction network analysis to identify the effect of the complement component genes C3, C5, C3AR1, and C5AR1 on 10 major functional and signaling pathways associated with human cancer." (PMID 34439277, 2021). "We found that the complements C3, C5, C3AR1, and C5AR1 have deregulated expression in human malignancies and are associated with activation of immune-related oncogenic processes and poor prognosis of cancer patients." (PMID 34439277, 2021). "Interestingly, deficiency of C3aR1, C5aR1, or C5aR2 produced effects opposite to those observed with C3 deficiency, underscoring the complexity of complement receptor signaling in cancer." (PMID 41300283, 2025). "Our data indicate that C5aR1 negatively regulates apoptosis in cancer cells by modulating cell survival pathways, such as NF-κB, and that attenuating such prosurvival signaling can render cancer cells more susceptible to death following RT." (PMID 37824211, 2023). "In particular, the effects of C5a deficiency and C5aR1 inhibition have been evaluated in mice with colorectal and lung cancer, demonstrating the efficient reduction of tumor size and the enhancement of the effects of anti-cancer chemotherapy." (PMID 35614037, 2022). "Studies indicate that some oncogenic proteins regulate the infiltration of immune cells into tumors; however, our correlation analysis revealed that the expression levels of C3, C3AR1, and C5AR1 were strongly associated with the infiltration of immune cells into tumors across the TCGA cancer types." (PMID 34439277, 2021). "However, in apparent contradiction to these findings, blocking of C3aR or C5aR1 in most cancer models has been associated with an increased infiltration of T cells both in the primary tumor and the metastatic niche." (PMID 31031765, 2019). "Antagonizing autocrine C3ar/C5ar1 signaling in eight human and murine cancers of diverse lineages was universally anti-mitotic and pro-apoptotic in vitro, and growth-repressive in vivo." (PMID 42274564, 2026). "Here, we demonstrate that ER stress-induced C5aR1 is internalised and accumulates intracellularly in cancer cells via endocytosis." (PMID 40695778, 2025). "Collectively, these results indicate that C5aR1 mediates cellular adaptation to hypoxic stress by modulating autophagy and apoptosis in cancer cells." (PMID 40695778, 2025). "In this study, we show that intracellular C5aR1 expression increases in a UPR-dependent manner in various cancer cells to mediate their adaptation to hypoxic stress." (PMID 40695778, 2025). "Here, we show that cancer cells under hypoxia and ER stress increase the expression of intracellular C5aR1 in a UPR-dependent manner." (PMID 40695778, 2025).
cancer (continued). "The C5aR1 inhibitor functions in both intracellular and extracellular PDAC, as C5a itself is a peptide that exerts its effects by binding to C5aR1 on the surface of target cells such as cancer cells and immune cells." (PMID 41044172, 2025). "Increased C5aR1 expression results in attenuated autophagy and apoptosis thereby increasing cancer cell survival under hypoxia (<0.1% O2)." (PMID 40695778, 2025). "Multiplex immunofluorescence for FAP and αSMA, two markers for cancer-associated fibroblasts, showed that the relative abundance of C5aR1+FAP+ cells and C5aR1+SMA+ cells was higher in cSCCs than in normal skin, AK, and cSCCIS." (PMID 40056975, 2025). "C5aR1 is highly expressed in various cancers, including lung, breast, and gastric cancers, and is associated with patient prognosis." (PMID 39368999, 2024). "Taken together, these data indicate that elevated C5aR1 levels and C5aR1 on macrophages is associated with ICB resistance in human cancer patients." (PMID 38802355, 2024). "C5AR1 expression in myeloid-derived suppressor cells promotes cancer metastasis and the infiltration of immunosuppressive leukocyte populations into the TME." (PMID 38002057, 2023). "Using a combination of RNA-Seq and in silico mining of DepMap, CanSAR, and patient data sets, we identified C5aR1 as a druggable target for enhancing stress-specific cancer cell death." (PMID 37824211, 2023). "Expression of C5aR1 on cancer cells enhances their motility, invasiveness and epithelial to mesenchymal transition." (PMID 36003145, 2022). "Since NETs levels were shown to be elevated in multiple advanced cancer patients, further studies should be pursued to understand more in depth the contribution of C5a/C5aR1 axis and NETosis specifically during skeletal colonization." (PMID 36003145, 2022). "Since the importance of complement system in cancer biology has been demonstrated, the role of C5a-C5aR1 axis in the pathogenesis of different types of cancer has been explored in several studies along with the potential therapeutic effect of its inhibition." (PMID 35614037, 2022). "We queried the effect of CNVs and differential methylation levels of C3/C5/C3AR1/C5AR1 on T-cell dysfunction phenotypes across the TCGA cancer types." (PMID 34439277, 2021). "Among the three cell types promoting T-cell exclusion, MDSCs and the M2 subtype of TAMs are negatively associated with the expression levels of C3, C5, C5AR1, and C3AR1, while only C3 expression shows a positive association with cancer-associated fibroblasts." (PMID 34439277, 2021). "In conclusion, the complement components C3, C5, C3AR1, and C5AR1 serve as attractive targets for strategizing cancer immunotherapy and response follow-up." (PMID 34439277, 2021). "We assessed the correlation of C3, C5, C3AR1, and C5AR1 expression with infiltrations of six types of immune cells across the TCGA cancer types." (PMID 34439277, 2021). "The complement components C3, C5, C3AR1, and C5AR1 serve as attractive targets for strategizing cancer immunotherapy and response follow-up." (PMID 34439277, 2021). "We used the differential gene expression module of TIMER to evaluate the differential expression of C3, C5, C3AR1, and C5AR1 between human cancer and normal tissues across the TCGA database." (PMID 34439277, 2021). "Collectively, C3, C5, C3AR1, and C5AR1 demonstrated context-dependent expression in and a prognostic impact on various cancer types." (PMID 34439277, 2021). "More biological evidence is required to further understand the role of the complement components C3, C5, C3AR1, and C5AR1 in cancer progression." (PMID 34439277, 2021). "We found that C3, C5, C3AR1, and C5AR1 expression is negatively associated with infiltrations of M2-TAMs and MDSCs but positively associated with CAF infiltrations in various cancer types." (PMID 34439277, 2021). "Myeloid cell-cancer cell communication analyses revealed activation of C5AR1/RPS19 and HLA-C/FAM3C pairs." (PMID 34326696, 2021).
cancer (continued). "This possibility and the complicated involvement of C5aR1 signaling pathway in cancer development and metastasis await further investigation." (PMID 33672651, 2021). "This study is in line with previous observations of an abnormal expression of complement proteins in different type of cancer, especially C1 complex, C3, C4, C5, C3aR, C5aR1, FB, FH, FI, CD46, CD55, CD59." (PMID 33113844, 2020). "This study also showed that pharmacologic blockade or genetic ablation of C5AR1 prevented metastatic potential of cancer cells." (PMID 33718121, 2020). "Another study reported increased cell invasiveness in response to C5a-induced secretion of metalloproteinases from C5aR1-expressing cancer cells and degradation of extracellular matrix (ECM), known to contribute to neoplastic progression." (PMID 31506518, 2019). "We propose that ER stress-induced intracellular C5aR1 may allow the cancer cell to adapt to this stress by limiting autophagy and apoptosis, thereby promoting a return to homoeostasis and cell survival." (PMID 40695778, 2025). "Furthermore, we also show that genetic and pharmacological inhibition of C5aR1 signalling decrease cancer cell survival under hypoxic conditions, with strategies able to inhibit intracellular C5aR1 pools showing the greatest effects on survival." (PMID 40695778, 2025). "Importantly, intracellular C5aR1 can be used as a new therapeutic target for resistant cancer cells in the hypoxic TME." (PMID 40695778, 2025). "These anaphylatoxins play important roles in the pathogenesis of allergy, autoimmunity, neurodegenerative diseases, cancer and infections through ligation of their receptors, i.e., the C3a receptor (C3aR), C5a receptor 1 (C5aR1), and the C5a receptor-like C5L2 (C5aR2)." (PMID 41373839, 2025). "Importantly, we demonstrate that genetic and pharmacological inhibition of C5aR1 decreases cancer cell survival under severe hypoxia." (PMID 40695778, 2025). "Using an integrated screening approach to identify cancer-specific vulnerabilities, we identified complement receptor C5aR1 as a druggable target, which when inhibited improved radiotherapy, even in tumors displaying immunosuppressive features and poor CD8+ T cell infiltration." (PMID 37824211, 2023). "In addition to cancer cells, osteoblasts also highly express C5aR1 further promoting a pro-metastatic environment." (PMID 36003145, 2022). "However, only anaphylatoxin receptors C5aR1 and C3aR, as well as anaphylatoxin C5a, have been targeted in anti-cancer therapy." (PMID 35053469, 2022). "Previous studies concluded that C5AR1 was highly expressed in certain types of cancer." (PMID 36230961, 2022). "Interestingly, these cancers are among the most mutated cancer types with respect to C3, C5, C3AR1, and C5AR1." (PMID 34439277, 2021). "Collectively, our study demonstrates that the complement component proteins C3, C5, C3AR1, and C5AR1 are candidate biomarkers for cancer diagnosis, prognosis, and therapy outcomes, and thus serve as attractive targets for strategizing cancer immunotherapy and the response follow-up." (PMID 34439277, 2021). "Similarly, myeloid cells communicate with cancer cells via C5AR1/RPS19." (PMID 34326696, 2021). "Our results suggest the involvement of C3 and C3AR1 in the resistance of human cancer cell lines to small molecules drugs, while the expression levels of C5AR1 and C3AR1 could predict the response to chemotherapy in breast, ovarian, colorectal, and GBM cancer patients." (PMID 34439277, 2021). "We next used other selective C5aR1 inhibitors, JPE-1375 and Avacopan, and found that both of these showed more significant effects on cancer cell viability than PMX205." (PMID 40695778, 2025). "In this study, we demonstrated that LukS-PV targeting C5aR1 inhibits HCC cell proliferation by the HDAC7-Wnt/β-catenin axis, suggesting the strong potential of LukS-PV as a therapeutic cancer drug for HCC treatment." (PMID 39736396, 2025).
cancer (continued). "Next, we tested the effects of these C5aR1 inhibitors on cell survival, and as expected, JPE-1375 and Avacopan significantly reduced cancer cell survival under hypoxia." (PMID 40695778, 2025). "We found that C3AR1 expression is higher in GBM as compared with all other cancers analyzed in TCGA, whereas Complement Receptor 1 (CR1), CR2, C1qR1 (CD93), and C5AR1 were expressed at varying levels." (PMID 39172519, 2024). "After exploring immune phenomenon scores through The Cancer Immunome Database (TCIA), we found that anti-CTLA-4 immunotherapy was better in the low C5aR1 expression score group." (PMID 36508191, 2023). "However, the function of C5aR1 on neutrophils during cancer progression remains unknown." (PMID 34312368, 2021). "While not yet extensively studied in GBM, C5AR1 has been validated as a druggable target in other cancer models." (PMID 40843669, 2025). "Inhibiting C5AR1 enhances chemotherapy response by involving the suppression of CD8+ T-cell cytotoxicity, and a study suggests C5AR1-dependent signaling as an important immunomodulatory program for combinatorial cancer immunotherapy." (PMID 38002057, 2023). "Studies had reported that C5aR1 recruited bone-marrow suppressor cells into inflamed CRC tissue through signal transduction to damage CD8+T cells and regulate the production of cytokines and chemokines, thus initiating the occurrence of cancer." (PMID 36192575, 2023). "Finally, TNFSF10—TNFRSF10B (TRIAL—TRIAL-R), SIRPA—CD47 (“don't eat me”), C5AR1—RPS19, and GAS6—AXL act as negative regulators of the innate immune system by inhibiting cytokine responses, phagocytosis of cancer cells, and promoting the immunosuppressive TME." (PMID 37823774, 2023). "Second, the results of this study could not serve the explanation of pathophysiological relevance of diverse expression of C5AR1, CLEC4A and NLRP3 in CD3+ T-lymphocyte amount cancer patient and healthy individuals." (PMID 36323738, 2022). "In addition, we found some up-regulated genes, ADRA2C, C3, and C5AR1, which were not previously reported in cancer stemness." (PMID 30420637, 2018).
infection (70 papers, 2011 to 2025). The state of being infected such as from the introduction of a foreign agent such as serum, vaccine, antigenic substance or organism. "Severe infection in C5ar1−/− mice was associated with diminished serum concentrations of IL-12, IL-27, and IFN-γ." (PMID 32733463, 2020). "C5ar1−/− mice suffered from a significantly higher relative weight loss, disease severity during infection that was associated with a ~20% increase in the mortality rate in the C5ar1−/− group as compared to control mice." (PMID 32733463, 2020). "We, therefore, used our CEACAM1-humanized mouse model in combination with deficiencies in C3 (C3−/-), C5 (C5−/-), C3aR1 (C3ar1-/-) C5aR1 (C5ar1−/-) or C5aR2 (C5ar2−/-) to monitor Nme nasal colonization following intranasal infection with 105 CFU." (PMID 31274379, 2019). "C5aR1-deficient (C5aR1-/-) mice showed a significant reduction in bacterial load, tubule injury and tubulointerstitial fibrosis in the kidneys following infection, compared with C5aR1-sufficient mice." (PMID 27370410, 2016). "One of the important observations in this study is that C5aR1 deficiency or blockade C5aR1 reduced bacterial load at all stages of infection studied, even at the early stage of infection (day 2 or 3 after inoculation)." (PMID 27370410, 2016). "Another strategy to reduce infection risk is to target C5a, a potent chemoattractant, or its receptor C5aR1 (CD88), a G protein-coupled receptor (GPCR) expressed on granulocytes monocytes/macrophages peripherally and on astrocytes and microglia (and at low level neurons and oligodendrocytes) in CNS." (PMID 30886620, 2019). "Our data demonstrate that C5aR1 deficiency or blockade not only reduces renal bacterial load at all stages of infection but also attenuates tissue inflammation and tubulointerstitial fibrosis, suggesting a pathogenic role for C5aR1 in experimental chronic kidney infection." (PMID 27370410, 2016). "Taken together, our findings suggest the involvement of the p38 MAPK signaling pathway in C5aR1-mediated neuropathological changes during EV-A71 infection." (PMID 39679722, 2025). "Taken together, our findings indicate that the activation of the C5a–C5aR1 axis in astrocytes facilitates the neuropathological changes resulting from EV-A71 infection, emphasizing the potential role of p38 MAPK-mediated CXCL1 production in these alterations." (PMID 39679722, 2025). "Key upstream receptors (TLR4, C5aR1) and downstream cytokines were analyzed to determine how infection activates TLR4–NF-κB- and GPCR-mediated pathways, and to evaluate the modulatory effects of L-Sepiapterin and CDDO-Me." (PMID 41294830, 2025). "Diseases that are predominantly driven by C5aR1 can be treated with antagonists such as Avacopan for ANCA-associated vasculitis, helping to retain the MAC for infection." (PMID 40122920, 2025). "Of the key complement factor receptors, only the Colonizing strain significantly increased intracellular C5aR1, while intracellular C3aR was unchanged in all infections." (PMID 40985395, 2025). "Compared with C5aR1 knockout mice, wild-type mice presented more severe symptoms and lower survival rates after EV-A71 infection." (PMID 39679722, 2025). "Overall, these findings indicate that the C5a–C5aR1 axis is activated in children with EV-A71 encephalitis and that complement activation has important prognostic value in patients with EV-A71 infection." (PMID 39679722, 2025). "To assess the clinical relevance of C5a–C5aR1 axis activation in EV-A71 infection, we analyzed plasma complement component levels in individuals with mild and severe EV-A71 infection, as well as in healthy controls." (PMID 39679722, 2025). "Neutrophils were the most abundant and highest C5aR1-expressing cell type in the alveolar space after infection." (PMID 39628481, 2024).